TXNIP (thioredoxin interacting protein)
Diseases named in the same sentence as TXNIP in open-access papers (continued):
Sharing a sentence is not in itself a finding about the gene and the disease.
diabetes (continued). "TXNIP is an early response gene highly induced by diabetes and hyperglycemia." (PMID 22474421, 2012). "The finding that AMPK mediates nutrient regulation of TXNIP may have important implications for the pathophysiology and treatment of diabetes." (PMID 22194917, 2011). "We decided to study the response of TXNIP-ROS-TRX axis in vitro as a mimicker of the in vivo situation involving a patient who either experiences GC-induced hyperglycemia or uses DEX in a condition of existing frank diabetes." (PMID 21910912, 2011). "Thus, classic mechanics explaining DNA methylation activity demonstrate that a higher expression of TXNIP could be related to diabetes pathogenesis." (PMID 40725425, 2025). "TXNIP (1 site) has consistently emerged as the most significant gene associated with T2D in previous EWAS studies due to its role in regulating pancreatic β-cells production and survival and has arisen as a novel potential therapeutic target in diabetes mellitus and its complications." (PMID 39827095, 2025). "TXNIP knockdown by small interfering RNA can overcome the diabetes-related pathologies of angiogenesis, cardiomyopathy, and renal injury, and alleviates the apoptosis and inflammation of retinal cells in diabetic mice, which indicates that TXNIP could act as a therapeutic target." (PMID 40559375, 2025). "In mice, the absence of TXNIP causes fasting hypoglycemia with a significant enhancement of glucose uptake by peripheral tissues, and a drug that inhibits TXNIP expression renders mice resistant to diabetes." (PMID 38329960, 2024). "Therefore, it is possible to utilize TXNIP as a biomarker for diabetes development." (PMID 36733403, 2023). "Therefore, the inhibition of TXNIP is a reasonable therapeutic strategy against diabetes." (PMID 37394581, 2023). "Similarly, inverse relationships between cg19693031 (TXNIP) and diabetes have been observed." (PMID 37779905, 2023). "In patients with diabetes, there is an increased expression of renal NOX5 associated with enhanced ROS formation and the upregulation of ROS-sensitive pathways as early growth response 1 (EGR-1), protein kinase C-α (PKC-α), and thioredoxin-interacting protein (TXNIP)." (PMID 36905456, 2023). "In addition, TXNIP is involved in the regulation of β-cell function, cellular glucose uptake and hepatic glucose output, overall providing adverse effects on glucose homeostasis and acting as a potential therapeutic target for diabetes." (PMID 35276968, 2022). "TXNIP overexpression in diabetes regulates the activity of the key cytokine VEGF in a glucose-sensitive manner, whereas a TXNIP knockdown by small interfering RNA (siRNA) can overcome the diabetes-related pathologies of angiogenesis and arteriogenesis and may help to recover an ischemic hindlimb." (PMID 33803178, 2021). "However, TXNIP rs7211 has not been found to be associated with retinopathy or with diabetes in Caucasian patients with type 2 diabetes (T2D)." (PMID 33567593, 2021). "TXNIP has been reported critical in diabetes mellitus (DM) by influencing glucose metabolism in pancreatic ß cells." (PMID 33323975, 2021). "Besides, direct gene editing of TXNIP in vivo, TXNIP modification in vitro may contribute for the advanced therapeutics in diabetes." (PMID 32824669, 2020). "Therefore, increased TxNIP O-GlcNAcylation in pancreatic islets could play a part in diabetes pathogenesis." (PMID 31164864, 2019). "Therefore, TXNIP represents a potential target for preventing ocular complications of diabetes." (PMID 28492550, 2017). "In addition, the CRISPR/Cas9 and TXNIP gRNA method employed in this study may also be a potential strategy for knocking out TXNIP and preventing DR progression, as well as other microvascular complications of diabetes." (PMID 28492550, 2017).
diabetes (continued). "The increased skeletal muscle TXNIP gene expression (and borderline reduced TXNIP DNA methylation) in the subgroup of 23 offspring with abnormal glucose tolerance is in support of previous findings of increased skeletal muscle TXNIP expression in subjects with prediabetes and diabetes." (PMID 29077742, 2017). "Immunohistochemical staining showed that diabetes mellitus resulted in significantly increased expression of type I collagen (P < 0.01) localized to the interstitial areas of diabetic kidneys, which was significantly attenuated by the administration of TXNIP DNAzyme (P < 0.01)." (PMID 27381856, 2016). "Since we previously demonstrated that RAGE induces TXNIP expression in retinal endothelial cells leading to chronic inflammation and ultimately inducing neurodegeneration in diabetic retina, we studied whether Aβ induces TXNIP expression in brain derived endothelial cells (RBE4)." (PMID 22482078, 2012). "Interestingly, TXNIP is necessary to mediate insulin resistance in diabetes." (PMID 22482078, 2012). "Thus, TXNIP is emerging as a critical link between hyperglycemia and beta-cell death in diabetes." (PMID 22194917, 2011). "Although TXNIP was initially identified as a protein interacting with thioredoxin and modulating cellular responses to oxidative stresses, it has the ability to inhibit glucose uptake and is being recognized as an important regulator of dysregulated metabolism in diabetes." (PMID 20844768, 2010). "miR-200 and miR-204 are involved in the TXNIP/miR-200/ZEB1/E-cadherin pathway, which activates the expression of TXNIP (thioredoxin-interacting protein), also known as TBP2, a well-known diabetes biomarker." (PMID 41153727, 2025). "Beyond insulin secretion, verapamil and other CCBs reduce the β-cell expression of thioredoxin-interacting protein (TXNIP), a proapoptotic factor overexpressed in diabetes, thereby inhibiting β-cell apoptosis and enhancing survival." (PMID 40710367, 2025). "Thioredoxin-interacting protein (TXNIP) is a member of the inhibitory protein alpha family and a central regulator of glucose and lipid metabolism, involved in diabetes-related vascular endothelial dysfunction and inflammation." (PMID 39350967, 2024). "TXNIP is a multifunctional protein, which plays an important role in oxidative stress, ERS, and inducing inflammation, and has been widely studied in diabetes and other chronic kidney diseases." (PMID 39768161, 2024). "Previous studies have demonstrated that the downregulation of TXNIP via MQEO reversed inflammation and oxidative markers in the kidney in a rodent model of type 1 diabetes mellitus." (PMID 38138443, 2023). "TXNIP is a key pathological regulator of several diseases, including CKD, diabetes, and neurodegenerative diseases, and is an attractive therapeutic target for the development of novel drugs." (PMID 37394581, 2023). "Metformin inhibits high glucose-induced TXNIP/NLRP3 inflammasome activation through AMPK activation in macrophages, which suppresses diabetes-mediated atherosclerosis." (PMID 37394581, 2023). "Treatment with metformin prevents TXNIP/NLRP3 inflammasome activation by suppressing ER stress in the adipose tissues of STZ-injected diabetic mice, thereby blocking diabetes-induced adipose dysfunction." (PMID 37394581, 2023). "Moreover, they showed that through inhibiting TXNIP expression, verapamil treatment significantly reduced β-cell apoptosis, promoted β-cell survival and glucose homeostasis, prevented diabetes progression or delayed diabetes development, and could even avert diabetes in streptozotocin-treated mice." (PMID 38089047, 2023). "Goto-Kakizaki (GK) rats, a model of type 2 diabetes mellitus (T2DM), have significantly reduced bone mass, although the expression of TXNIP in the bone tissue is significantly increased." (PMID 36059548, 2022). "TXNIP, which is involved in the activation of the NLRP3 inflammasome, is closely related to the onset of type 2 diabetes mellitus." (PMID 36452319, 2022).
diabetes (continued). "Some phytochemicals can exert powerful anti-oxidation and anti-inflammatory effects by inhibiting the combination of TXNIP and NLRP3 and have significant beneficial effects on inflammation, cancer, diabetes, and other diseases." (PMID 36059548, 2022). "A study in a mouse model of diabetes also shows the excess of ROS and the establishment of oxidative stress resulting from the decrease in the activity of TRX due to its inhibition by TXNIP." (PMID 33567593, 2021). "TXNIP upregulation and the subsequently increased formation of the TRX-TXNIP complex is a proposed pathway by which diabetes induces insufficient angiogenesis and thereby exacerbates myocardial ischemia injury." (PMID 33567593, 2021). "Evidence has shown that the NLRP3 inflammasome, IL-1β, thioredoxin-interacting protein (TXNIP), and pyroptosis play vital roles in the development of diabetes." (PMID 34356130, 2021). "It has previously been known that TXNIP/NLRP3 inflammasome is activated by ER stress in several diseases, sunch as diabetes mellitus, some neurodegenerative diseases and atherosclerosis, however, related data is scarce in ischemic retinopathy." (PMID 33933165, 2021). "TXNIP and TRX play antagonistic roles in β-cell function and diabetes pathophysiology, and accumulation of TXNIP in insulinoma cells is typically a sign of oxidative stress." (PMID 34439408, 2021). "In pancreatic beta-cells, the expression of TXNIP is downregulated by insulin and is consistently increased in patients diagnosed with T2DM (type 2 diabetes mellitus)." (PMID 32973739, 2020). "One week after the induction of diabetes, the NCV of DM rats was unchanged, whereas TXNIP expression was increased, indicating that the upregulation of TXNIP occurred prior to the neurological deficit." (PMID 32774321, 2020). "The inverse association between DNA methylation and UACR was stronger in those with diabetes (cg14476101 in PHGDH, cg19693031 in TXNIP, and cg06690548 in SLC7A11) or those who were obese (cg06690548 in SLC7A11)." (PMID 32917208, 2020). "A number of different classes of agents can modulate TXNIP expression, including PPAR-γ agonists, which include classes of drugs with insulin-sensitizing properties used for treating diabetes." (PMID 33302545, 2020). "We identified significant associations between cg10601624, cg06690548 (SLC7A11), cg19693031 (TXNIP), and cg00574958 (CPT1A) and TOD in the kidney even further after adjustment for BMI, smoking status, and diabetes." (PMID 32917208, 2020). "In summary, these results suggest FMK protects against HG-induced β-cell dysfunction and against TXNIP expression via ChREBP regulation in pancreatic β-cells, and that FMK be viewed as a potential therapeutic for the treatment of diabetes." (PMID 31505737, 2019). "Thioredoxin-interacting protein (TXNIP), which is an early response gene highly induced by diabetes and hyperglycemia, acts as a mediator of cellular metabolism." (PMID 31118974, 2019). "In a rat model of diabetes, H3K27me at the enhancer site of zeste 2 repressive complex 2 subunit (EZH2) dampens the expression of the endogenous antioxidant inhibitor thioredoxin-interacting protein (TXNIP) via repressing the transcription factor PAX6." (PMID 31687085, 2019). "The evidence has shown that the NLRP3 inflammasome, IL-1β, thioredoxin-interacting protein (TXNIP), and pyroptosis play vital roles in the development of diabetes." (PMID 31835423, 2019). "The diabetes-induced upregulation of VEGF and proteins in the TXNIP/NLRP3 pathway was prevented by vitamin D3 treatment." (PMID 29682582, 2018). "Interestingly, NLRP3 deficiency did not prevent diabetes in Akita mice, suggesting other inflammasomes or TXNIP activities may play a role." (PMID 29556237, 2018). "Recent findings demonstrate a potential role for TXNIP in innate immunity via the NLRP3 inflammasome activation and release of IL-1β in diabetes and oxidative stress." (PMID 26881256, 2016).
diabetes (continued). "An understanding of the TXNIP-HIF-1α-VEGF-A axis and its temporal response under chronic hyperglycemia in Muller cells that enhances VEGF-A expression in diabetes will be important." (PMID 22474421, 2012). "We have recently shown that TXNIP expression is increased in the retina of STZ-induced diabetic rats at both 4 and 8 weeks of diabetes duration and mediates inflammation, gliosis/fibrosis, and apoptosis of retinal cells." (PMID 22474421, 2012). "In this study, we further support our previous findings by showing that the expressions of TXNIP, pro-inflammatory IL-1β, iNOS, and pattern recognition receptors TLR4 and P2X7R in the retina are elevated at 4 weeks of diabetes." (PMID 22474421, 2012). "Recent findings further demonstrate a potential role for TXNIP in innate immunity via the NOD-like receptor-NLRP3/caspase-1 inflammasome activation and release of IL-1β in diabetes and oxidative stress." (PMID 22474421, 2012). "This change was accompanied by increased hippocampal neuron cell apoptosis, and upregulated expression of thioredoxin-interacting protein (TXNIP), interleukin IL-1β and tumor necrosis factor TNF-α, suggesting diabetes-induced endoplasmic reticulum stress and neuroinflammation." (PMID 41277875, 2025). "TXNIP activates NLRP3 inflammasome complex formation, triggers mitochondrial stress-induced apoptosis and inflammatory cell death, as a potential therapeutic target in various diseases, such as diabetes, chronic kidney disease, and neurodegenerative diseases." (PMID 39744566, 2025). "Similarly, in mice, oral verapamil lowered TXNIP expression, increased endogenous insulin levels, and reduced β-cell apoptosis, rescuing the mice from streptozotocin (STZ)-induced diabetes." (PMID 38891081, 2024). "While the involvement of miR-20a in the inflammasome pathway in diabetes has not been reported, its inclusion in the miR-17-92 cluster alongside miR-17 suggests a potential similar role in DR through the regulation of TXNIP expression." (PMID 39220230, 2024). "It is also worth noting that neither non-specific downregulation with verapamil, nor specific inhibition with TIX100 completely suppresses TXNIP expression, yet effectively protected against diabetes in different preclinical models." (PMID 39429740, 2024). "In addition, elevated ROS levels can induce the dissociation of thioredoxin-interacting protein (TXNIP) from the TXNIP/ thioredoxin (TRX) complex, as well as promote the binding of TXNIP with NLRP3 to participate in its activation during diabetes." (PMID 36978920, 2023). "A recent study demonstrated the existence of ubiquitous TXNIP overexpression in CBATXNIP/+ mice, which aggravated the severity of streptozotocin-induced diabetes; however, this study did not report the influence of TXNIP overexpression on cardiac injury." (PMID 37850269, 2023). "Thioredoxin-interacting protein (TXNIP) is one of the α-arrestin proteins, known as the central regulator of glucose and lipid metabolism, which can participate in the regulation of related diseases, such as diabetes and inflammation." (PMID 35956280, 2022). "TXNIP plays a potential role in sterile inflammatory processes and innate immunity through the activation and releasing of IL-1β by the NLRP3 inflammasome in diabetes and oxidative stress." (PMID 36017183, 2022). "Reactive oxygen species (ROS) formation and thioredoxin-interacting protein (TXNIP, a pro-oxidant protein), were also markedly increased in NDM islets at day 15 of diabetes, suggesting increased oxidative stress in early stages of diabetes." (PMID 35180212, 2022). "Moreover, it is also intriguing to test the role of TXNIP in the prolonged IGF1-induced senescence phenotype since TXNIP is highly expressed in the late stages of aging and diabetes as an inflammatory marker and, conversely, as a tumor suppressor in cancer." (PMID 36291127, 2022).
diabetes (continued). "Several studies have revealed upregulation of TXNIP in diseases like type 2 diabetes mellitus (T2DM), type 1 diabetes mellitus (T1DM), cardiovascular diseases, ischemic stroke, and cataract as well as neurodegenerative disorders such as Alzheimer’s disease (AD), and Parkinson’s disease (PD)." (PMID 33803178, 2021). "The inhibition of TXNIP expression, inflammation, and ER stress through the activation of the adenosine monophosphate‐activated protein kinase (AMPK) pathway establishes a protective effect against retinal neurodegeneration in diabetes." (PMID 34401074, 2021). "However, this is the first evidence that TXNIP is directly required for NLRP3-inflammasome activation and retinal microvascular dysfunction in a model of HFD-induced insulin resistance and pre-diabetes." (PMID 32492941, 2020). "To summarize, our study provided evidence that punicalagin can alleviate diabetic nephropathy, and the effect is associated with downregulating the expression of NOX4, inhibiting TXNIP/NLRP3 pathway-mediated pyroptosis, suggesting its therapeutic implications for complications of diabetes." (PMID 32456088, 2020). "Interestingly, the thioredoxin-interacting protein (TXNIP) was reported to regulate the miR-204-MAFA-insulin pathway contributing to glucose metabolism and diabetes progression." (PMID 29209045, 2017). "Interestingly, thioredoxin-interacting protein (TXNIP) and islet amyloid polypeptide (IAPP) have also been shown to be up-regulated by glucose and diabetes and to be involved in β-cell apoptosis and inflammation." (PMID 27999212, 2017). "A previous study has shown that lack of TXNIP protects against diabetes and glucotoxicity-induced β-cell apoptosis." (PMID 25339452, 2015). "Recent knockout studies, suggested that inhibition of TXNIP/TBP-2, up regulates both insulin sensitivity and glucose-stimulated insulin secretion in diabetes, and might present a novel therapeutic approach for T2DM." (PMID 24624334, 2014). "Nonetheless, a role for TXNIP in Muller glia reactivity, innate immune response, ER stress, and inflammation under chronic hyperglycemia and diabetes has not been investigated before." (PMID 22474421, 2012). "In addition, we observed that at 8 weeks of diabetes, formation of LG3B puncta occurs in the retina and they colocalize with TXNIP (unpublished data)." (PMID 22474421, 2012). "Interestingly, in human, the absence of TXNIP in a family led to lactic acidosis and diabetes but no cancer was reported." (PMID 40260243, 2025). "Overall, Snhg15 overexpression may improve endothelial function during diabetes and thus erase the negative effect of TXNIP in the spinal cord of mice." (PMID 41144575, 2025). "IRE1α cleavage of miR17 leads to thioredoxin-interacting protein (TXNIP) accumulation, the activation of the NLRP3 inflammasome, and caspase-1-dependent interleukin (IL)-1β production, which can trigger pyroptosis that contributes to diabetes progression in humans and mice." (PMID 38744890, 2024). "As TXNIP has been considered a promising therapeutic target for diabetes 52, targeting TXNIP may be an ideal therapeutic strategy for patients with both NASH and diabetes." (PMID 37153733, 2023). "Furthermore, TXNIP can be induced by ROS, leading to NLRP3 activation in diabetes." (PMID 36017183, 2022). "Taken together, these findings suggest FMK may protect against HG-induced β-cell dysfunction and TXNIP expression by ChREBP regulation in pancreatic β-cells, and that FMK is a potential therapeutic reagent for the drug development of diabetes and its complications." (PMID 31505737, 2019). "As shown herein, TXNIP-inhibiting TRX activity is highly regulated by glucose, hitherto we suggest that this protein may play a major role in translating the biological consequences of a metabolic condition such as diabetes in cancer biology." (PMID 17555594, 2007).